EGFR (epidermal growth factor receptor)
Diseases named in the same sentence as EGFR in open-access papers (continued):
Sharing a sentence is not in itself a finding about the gene and the disease.
cancer (continued). "A number of findings have suggested that honokiol targets multiple signaling pathways, including NF-ҡB, STAT3, epidermal growth factor receptor (EGFR), and mammalian target of rapamycin (m-TOR), which play an important role in cancer initiation and progression." (PMID 29321719, 2018). "Meanwhile, the connection between Fas and EGFR through which the pro-survival mode of Fas heightens the EGF-induced EGFR signaling in cancer was never addressed." (PMID 30127519, 2018). "We also observed a positive correlation between SOX2 and EGFR expression in stage IV metastatic endometrial carcinoma, but not in early stage cancer." (PMID 30510261, 2018). "Given our findings, it will be important to assess whether low expression of the 80 confirmed genes is correlated with poor patient survival in other cancers where RAS signaling is elevated, such as EGFR or RAS-GAP (NF1) tumors." (PMID 30325918, 2018). "Furthermore, we also demonstrated that abolishing EGFR activation by antibody treatment suppressed AKT and NFκB phosphorylation and cancer cell activation in HNSCC." (PMID 30148841, 2018). "Our data provides new information suggesting that AR, EGFR and MMP-9 are interconnected and may play important roles during cancer progression from androgen-dependent state to castration-resistant state." (PMID 30134822, 2018). "We previously developed EMab-134, a novel anti-EGFR monoclonal antibody (mAb), which reacts with endogenous EGFR-expressing cancer cell lines and normal cells independent of glycosylation in Western blotting, flow cytometry, and immunohistochemical analysis." (PMID 29872734, 2018). "A meta-analysis of advanced BRAF mutant cancers treated with either cetuximab or panitumumab plus chemotherapy found that anti-EGFR therapy did not influence survival benefit compared to control regimens." (PMID 30598662, 2018). "Although cilia house a number of oncogenic molecules (including Smoothened, KRAS, EGFR, and PDGFR), their precise role in cancer remains unclear." (PMID 29874589, 2018). "Gefitinib treatment blocked the cancer cell migration, suggestive of the negative correlation of cancer cells-expressing T-cadherin and EGFR activation on endothelial cells." (PMID 29455663, 2018). "In human cancers, MET amplification and protein overexpression have been detected in gastric carcinoma, medulloblastomas and NSCLCs with acquired resistance to EGFR-TKI." (PMID 30404198, 2018). "Importantly, the three recombinants generated in this study were all able to infect human cancer cells expressing the targeted receptors, i.e., PSMA, EGFRvIII, or EGFR." (PMID 29966356, 2018). "The second class of small molecules directed to tyrosine kinase proteins was represented by Gefitinib (Iressa®) and Erlotinib (Tarceva®) both directed to the EGFR ATP-binding site and able to inhibit the abnormal activation of MAPK and PI3K/AKT pathways overexpressed in cancer cells." (PMID 30483135, 2018). "In the same way, the loss of KEAP1 by the CRISPR-Cas9 system cooperates with the tumor mutational landscape in modulating the response to BRAF, MEK, EGFR, and ALK inhibition and in allowing cancer cells to increase their ability to resist to treatments and proliferate." (PMID 29643973, 2018). "In addition, atypical NF-κB pathways, as in the case of epidermal growth factor receptor (EGFR) tyrosine kinase-dependent NF-κB activation, were likewise described to promote cancer." (PMID 29673141, 2018). "By inhibiting the Eps8/EGFR interaction, peptide 327 and TAT-327 may serve as novel peptide inhibitors, which could provide an innovative approach for treating various cancers." (PMID 29515106, 2018).
cancer (continued). "EGFR is known to regulate β-catenin signaling during development and in various cancers, but the effects of EGFR activity on β-catenin stability and activation have not been reported." (PMID 30097569, 2018). "We noticed that, although identified independently, several of these aberration hubs were connected together through protein-protein interactions and formed a protein network that included several known cancer driver factors such as MYC, EGFR, PIK3C2B, CDK1, and KDR." (PMID 29861861, 2018). "The effects of Smurf2 depletion on EGFR-negative cancer cells, normal fibroblasts, and on normal epithelial cells were minor." (PMID 30116722, 2018). "To explore cross-cancer predictive potential for targeted therapeutics, we applied CONCORD to two targeted therapeutic agents: Erlotinib (an epidermal growth factor receptor (EGFR) tyrosine kinase inhibitor) and Vemurafenib (a B-RAF inhibitor)." (PMID 29416679, 2018). "A further unexpected result was that older patients with non-squamous EGFR wild-type carcinoma (≥75 years) tended to live longer than their younger counterparts." (PMID 29587656, 2018). "Although the tumors lacking mutations in EGFR and KRAS showed a higher mutational/candidate neoantigen level than KRAS-mutant carcinomas, this difference was not statistically significant." (PMID 30097571, 2018). "EGF treatment also did not foster the formation of EpICD in whole-cell lysates or in cytoplasmic and nuclear extracts of Kyse30 and HCT8 cells, so we conclude that EGFR-dependent RIP of EpCAM is not a common process in carcinoma cells." (PMID 30261040, 2018). "Crosstalk between EGFR and COX-2 has been observed in other cancer types, but to our knowledge, the current study is the first to reveal the regulation of COX-2 by EGFR signaling in IBC and the positive correlation between EGFR and COX-2 expression in IBC patient samples." (PMID 28978083, 2017). "Currently, about EGFR and TRF expression in human cancer is few." (PMID 28430586, 2017). "Particularly interesting was the observation that the focal amplifications of receptor tyrosine kinases, including ERBB2, EGFR, MET, FGFR1 and FGFR2, are markedly more frequent in esophageal adenocarcinomas (42%) than in gastric (28%) and colorectal (14%) cancers." (PMID 28930282, 2017). "Blockade of the EGFR-NF-κB-FOXC1 pathway may provide treatment modalities for BLBC and other cancers." (PMID 28629477, 2017). "Moreover, CMP treatment in mice significantly reduced the expression levels of ki-67, p-EGFR, and p-STAT3 in cancer tissues." (PMID 29212184, 2017). "Translocated EGFR/ERBB family proteins function as positive regulators of transcription, DNA replication, and DNA repair, resulting in proliferation, angiogenesis, and metastasis of cancer cells." (PMID 29140271, 2017). "EGFR TKIs induce apoptotic cell death rather than cytostatic effects in cancer cells by controlling the expression of Bcl-2 family proteins." (PMID 29140271, 2017). "IHC and FISH detection methods for human epidermal growth factor receptor-2 (HER2), epidermal growth factor receptor (EGFR) and programmed death ligand-1 (PD-L1) were recently approved by the Food and Drug Administration (FDA) as routine clinical practice for cancer patients." (PMID 29246028, 2017). "PA might inhibit the cancer by decreasing EGF, EGFR, VEGF, Fit-1 expressions, and Res could raise these effects." (PMID 28978315, 2017). "Previous studies have linked GPR30 expression to the non-receptor tyrosine kinase (Src)-dependent activation of EGFR signaling in a variety of estrogen-responsive cancer cells." (PMID 29096683, 2017).
cancer (continued). "In addition, the EGFR-targeting Nbs, 17864-L(x)-EGa1-PEG and AG538-loaded nanobody-liposomes, have also been tested as anti-cancer agents." (PMID 28469136, 2017). "We sequenced specific exons of 16 cancer-related genes, including the most clinically relevant genes such as KRAS, NRAS, EGFR, BRAF, cKIT, as well as other targetable genes that are known to be somatically altered in solid cancers based on recent scientific and clinical literature." (PMID 28404952, 2017). "We also demonstrated that knockdown of EGFR, BRD9 and PPFIA1, which showed frequently copy-number gain at the genomic level, significantly inhibited cancer cell proliferation, indicating that these genes may play important oncogenic roles in ESCC." (PMID 28548104, 2017). "The human GlycoExpress expression system was developed to produce biotherapeutics with optimized glycosylation and used here to generate a panel of IgA isotype antibodies directed against targets for solid (TA-mucin 1, Her2, EGFR, Thomsen–Friedenreich) and hematological (CD20) cancer indications." (PMID 28952521, 2017). "Furthermore, preclinical studies have shown that EGFR− and HER2-driven cancers show differential response to targeted therapies." (PMID 28446242, 2017). "Fundamentally, the clinical efficacy of EGFR antagonists in cancer treatment was an unexpected finding, as the EGFR is ubiquitously expressed throughout the human body and not itself an oncogene." (PMID 28970798, 2017). "Here, a novel candidate EGFR-TKI, cAMP-H3BO3 complex, is investigated for its ability to reversibly bind to the EGFR ATP-binding site to prevent EGFR signal transduction and subsequently inhibit cancer cell growth." (PMID 28915593, 2017). "Previous studies show that EMMPRIN can induce cancer aggressiveness and angiogenesis via up-regulating the expressions of vascular endothelial growth factor (VEGF) and epidermal growth factor receptor (EGFR), and promote invasion and metastasis by the up-regulation of matrix metalloprotease (MMP)." (PMID 29282042, 2017). "Interestingly, three of the 29 subtype-specific ceRNA hubs, namely EGFR, IL6ST and MET, are listed in the Cancer Gene Census of the COSMIC database." (PMID 28052038, 2017). "Daphne W Bell receives royalties as a co-inventor on U.S. Patent No.7,294,468 “Method to Determine Responsiveness of Cancer to Epidermal Growth Factor Receptor Targeting Treatments”, which is licensed to Esoterix Genetic Laboratories LLC." (PMID 29137450, 2017). "Despite decades of research in the epidermal growth factor receptor (EGFR) signalling field, and many targeted anti-cancer drugs that have been tested clinically, the success rate for these agents in the clinic is low, particularly in terms of the improvement of overall survival." (PMID 28166195, 2017). "However, in other contexts, if KRAS and PIK3CA or EGFR and PIK3CA were tested, then testing for only two genes would be more expensive than the cancer panel." (PMID 28196074, 2017). "Even for genes that were significant in MutSigCV, oncodomain hotspots are more sensitive as they identify those same genes as significant in more cancer types for which they are known to play a role like BRAF in STAD, GBM, and UCEC and EGFR in COAD, STAD, and SKCM." (PMID 28426665, 2017). "Among EGFR downstream pathways, the AKT/mTOR pathway is upregulated in most cancers." (PMID 29234489, 2017). "We have shown that the EGFR mutational profile was not significantly different between LUAD and LSCC cancer types." (PMID 28436422, 2017).
cancer (continued). "There are many types of autocrine growth factors, with the major ones in cancer being vascular endothelial growth factor (VEGF), epidermal growth factor (EGF), insulin-like growth factor-2 (IGF-2), epidermal growth factor receptor (EGFR) and 5-hydroxytryptamine (5-HT; serotonin), to name a few." (PMID 28410237, 2017). "Most of the classic protein cancer biomarkers, such as epidermal growth factor receptor (EGFR), have been found on non-malignant cells, albeit usually at lower levels than cancer cells." (PMID 29156833, 2017). "While MET-amplified cancer cells do not respond to EGFR-targeting drugs, they are uniquely sensitive to anti-MET therapy." (PMID 28420162, 2017). "Treatment with CAT-SKL—a re-engineered protein form of the antioxidant enzyme catalase—inhibited cancer stem-like cells (CSCs), and treatment with the EGFR-specific SMKI erlotinib inhibited non-CSCs." (PMID 28281569, 2017). "A dual inhibitor of both EGFR and ErbB2 tyrosine kinases activity, lapatinib, had been applied mainly in metastatic breast cancer, since in other types of cancer it did not act as an effective inhibitor of the phosphorylation." (PMID 28286519, 2017). "Interestingly, in KRAS wild-type cell lines derived from colorectal cancer, inhibition of EGFR signalling was less effective in 3D cultures grown in laminin-rich extracellular matrices, emphasizing the influence of the ECM on cancer growth and drug response." (PMID 28417948, 2017). "EGFR and VEGF have been believed to promote cancer growth and metastasis." (PMID 28202050, 2017). "EGFR and SRC have been reported to functionally synergize to form more aggressive cancers." (PMID 28513565, 2017). "Exosome-mediated EGFR activates liver HGF, thus preparing ‘soil' for future cancer cell metastasis." (PMID 28393839, 2017). "REP1 knockdown induces cell growth inhibition in cancer cells, but not normal cells, via downregulation and inactivation of EGFR and STAT3, respectively." (PMID 28230863, 2017). "These segments contain known cancer genes including MYC, EGFR, ERBB2 CDKN2A, RB1 and STK11." (PMID 28686671, 2017). "The EGFR and the TGFBR1 signalling pathways alone play a role in cancer development." (PMID 28719611, 2017). "Indeed, 97% of cancers with HER2 phosphorylated at Y1248 exhibit detectable EGFR32 and HER2 stabilizes EGFR by reducing Y1068 phosphorylation." (PMID 28623316, 2017). "Epidermal growth factor receptor (EGFR), a tyrosine kinases receptor (RTK) belongs to the ErbB family, has been found to be over-expressed in many types of cancer, making it a typical target for cancer therapy." (PMID 29019267, 2017). "The epidermal growth factor receptor, EGFR, is a transmembrane receptor tyrosine kinase (RTK), known to be overexpressed in approximately 90% of tumors that strongly affects the quality of life and outcomes of cancer patients all over the world." (PMID 28218686, 2017). "In an attempt to develop potent and selective antitumor agents, a series of quinazoline- and thiourea-containing sorafenib derivatives were designed and synthesized, and their inhibitory activities against EGFR, VEGFR-2, and three cancer cell lines were evaluated." (PMID 29295519, 2017). "Compound 3l not only demonstrated strong anti-proliferation activities against the two cancer cell lines, but also showed significant inhibitory activity (LC50 = 37.66 nM) towards EGFR, comparable to that of the medicinally important EGFR inhibitor Gefitinib (LC50 = 31.44 nM)." (PMID 29156606, 2017). "HER1/EGFR and HER2/c-erb-B2 are the most thoroughly investigated family members and have been documented to be involved in the pathogenesis of several types of cancers." (PMID 28210516, 2017).
cancer (continued). "Transferrin, epidermal growth factor receptor (EGFR), folate receptor, CD44 (known as HCAM or homing cell adhesion molecule) receptor, integrins, and low density lipoprotein receptors are commonly exploited for targeted drug delivery in cancer cells." (PMID 28346381, 2017). "In an attempt to investigate underlying molecular mechanisms of c-MET/EGFR reduction in NRF2-silenced cancer cells, we hypothesized the potential involvement of miRNAs in the dual regulation of c-MET and EGFR." (PMID 29291022, 2017). "Furthermore, a single-chain variable fragment targeting epidermal growth factor receptor (EGFR), transferrin, and an aptamer targeting a prostate-specific membrane have been used to impart AuNPs with the ability to target cancer cells." (PMID 28754120, 2017). "Another line of study suggests deregulated EGFR pathway induces TA via PI3K/AKT-mediated direct phosphorylation and hypoxia-inducible factor-1α (HIF-1α)-mediated transcriptional regulation of hTERT in cancer." (PMID 28740573, 2017). "Since, EGFR activation up-regulated glycolysis in EGFR mutant cells but not in EGFR wild-type cancer cells and normal cells, thus, it is predictable that AMPK activation will suppress cell viability more in EGFR mutant cells and normal cells." (PMID 29221189, 2017). "A likely lncRNAs profile will include, among others, HOTAIR, MEG3, NEAT1, UCA1, and/or AK126698 in cancer-drugs cisplatinum-based therapies, and the recently proposed GAS5, UCA1, BC087858 and SOX2-OT involved in the gene-target therapies as EGFR-TKIs based oncological treatments." (PMID 28904641, 2017). "EGFR can regulate AKT, one of the most important signalling pathways activated in human cancer." (PMID 28465354, 2017). "Moreover, in view of a critical role of EGFR in cancer, it would be of great importance to further dissect α1 NKA-mediated regulation of EGFR and its potential role in cancer biology." (PMID 28613263, 2017). "Mutations in tyrosine kinase domain of EGFR gene (18–22 exons) are important predictive markers for clinical benefit from EGFR tyrosine kinase inhibitor (TKI) therapies in development for non-small cell lung cancer (NSCLC), one of the most common and deadly cancer." (PMID 28583065, 2017). "Since our results showed a dual inhibitory role of miR-206 in c-MET and EGFR expression in NRF2-silenced SKOV3 and A498 cells, we asked whether this was a common biological link in other types of cancer cells." (PMID 29291022, 2017). "In addition, overexpression of FAM83A increases cancer cell proliferation and invasion, phosphorylates c‐RAF and PI3K p85, upstream of MAPK and downstream of EGFR, and confers resistance to EGFR‐TKI." (PMID 28078827, 2017). "The first two members of this family, EGFR and HER2, have been implicated in tumorigenesis and cancer progression for several decades, and numerous drugs have now been approved that target these two proteins." (PMID 28725482, 2017). "For effective cancer therapy, PI3K inhibitors in combination with pathways targeting Akt, mTOR, RTKs (receptor tyrosine kinases), MAPK (mitogen activated protein kinase), EGFR (epidermal growth factor receptor), HER2 (human EGF receptor 2), DNA repair enzymes." (PMID 29311925, 2017). "Both EGFR and FLT4 have been shown to be silenced by DNA methylation in cancer." (PMID 27911866, 2017). "EGFRvIII appears to meet most of the criteria of ideal antigen for CAR-T therapy, for it is the most commonly altered form of EGFR in cancers with no expression in normal tissues." (PMID 28356156, 2017). "Western blot analysis revealed EGFR and VEGF expression in this cancer cell line." (PMID 28432289, 2017).